OPCML (opioid binding protein/cell adhesion molecule like)
Diseases named in the same sentence as OPCML in open-access papers (continued):
Sharing a sentence is not in itself a finding about the gene and the disease.
cancer (continued). "Thus, we know that OPCML plays a critical role in negatively regulating cancer initiation and progression through its interaction with RTKs at their site of action, the external leaflet of the cell membrane of ovarian cells." (PMID 40699804, 2025). "OPCML, a tumor suppressor gene, is frequently silenced epigenetically in ovarian and other cancers." (PMID 31316070, 2019). "OPCML hypermethylation is considered a promising cancer biomarker." (PMID 30555700, 2018). "In addition, poorly differentiated cancers exhibited a significantly lower expression of OPCML protein than well and moderately differentiated ones." (PMID 28407749, 2017). "We speculate that epigenetic silencing of OPCML would impair the cellular protective response to environmental stresses in normal cells, thus promoting the development of cancers." (PMID 18714356, 2008). "As a master regulator of RTK activity through non-canonical, extracellular mechanisms, OPCML offers several promising therapeutic avenues to combat drug resistance in cancer, particularly redundant by-pass overlaps between RTKs." (PMID 40699804, 2025). "OPCML was consistently downregulated in GBM and across multiple cancers." (PMID 41561740, 2025). "Similarly, OPCML’s repression of AXL, also in synergy with selective inhibitors, can more effectively target EMT in cancer cells, especially as an approach to overcome resistance to prior chemotherapies." (PMID 40699804, 2025). "Preclinical evidence from different cancers (including OC) showed that hypomethylating agents can re-sensitize cancer cells to platinum in vitro and in murine models by restoring tumor-suppressor genes expression (such as RASSF1A, BRCA1, DAPK, OPCML, and hSulf-1)." (PMID 34948446, 2021). "There is no evaluation of OPCML methylation as a differential marker for cancer patients." (PMID 30832707, 2019). "In addition, ectopic expression of OPCML in carcinoma cells lacking its expression led to dramatic anchorage-dependent and –independent growth inhibition." (PMID 18714356, 2008).
adenocarcinoma (5 papers, 2007 to 2021). A common cancer characterized by the presence of malignant glandular cells. "Five remaining loci, CDH13, CDX2, OPCML, SFRP1 and TWIST1 were designated as “late” loci; significantly elevated DNA hypermethylation was only detected in adenocarcinoma, as compared with AIS." (PMID 21731750, 2011).
psychiatric disorder (1 paper, 2024). A disorder characterized by behavioral and/or psychological abnormalities, often accompanied by physical symptoms. "Furthermore, a maternal function of these genes might account for differences in the severity or onset of NEGR1- or OPCML-linked psychiatric disorders." (PMID 38540422, 2024).
OPCML also shares sentences with these, for which no sentence is quoted: cervical carcinoma (3 papers); liver cancer (3); lymphoma (3); /T-cell lymphoma (1); alcohol dependence (1); amyotrophic lateral sclerosis (1); autoimmune disease (1); bacterial infections (1); bipolar disorder (1); Burkitt lymphoma (1); cholangitis (1); cholelithiasis (1); chordoma (1); clear renal cell carcinoma (1); Cognitive impairment (1); gastric adenocarcinoma (1); gastric neoplasm (1); hereditary colorectal cancers (1); Hodgkins lymphoma (1); liver steatosis (1); lymphoproliferative disorders (1); Lynch syndrome (1); major depressive disorder (1); malignant neoplasms of the prostate (1); myasthenia gravis (1); myeloid leukemia (1); neurodegenerative disease (1); neurological disorders (1); opioid use disorder (1); osteosarcoma (1).
A further 6 diseases each share a sentence with OPCML in 1 paper.